CRP (C-reactive protein)
Diseases named in the same sentence as CRP in open-access papers (continued):
Sharing a sentence is not in itself a finding about the gene and the disease.
coronary artery disease (continued). "Therefore, we undertook this study to prospectively determine the stability of serial CRP measurements over one year in stable subjects with several distinct manifestations of coronary artery disease (CAD) and in a group without CAD while carefully controlling for known confounders." (PMID 23579782, 2013). "The observed relations were not substantially changed on exclusion of two subjects with an elevated level of C-reactive protein (CRP) (>5 mg/L) and after limitation of the analysis either to 33 boys or to 30 subjects with a negative parental history of premature coronary artery disease." (PMID 23203136, 2012).
pneumonia (985 papers, 2004 to 2026). An acute, acute and chronic, or chronic inflammation focally or diffusely affecting the lung parenchyma, caused by an infection in one or both of the lungs (by bacteria, viruses, fungi, or mycoplasma.). "For example, research indicates that elevated leukocyte counts and CRP levels are strongly associated with more severe pneumonia cases, often necessitating more intensive treatments." (PMID 41180631, 2025). "In children with severe pneumonia, higher serum CRP levels were associated with persistent fever and longer hospital stays." (PMID 40529154, 2025). "The univariate logistic regression analysis revealed that age (over 60 years), CRP, IL-6, D-dimer, hemoglobin concentrations, and platelet count were associated with an increased risk of pneumonia." (PMID 40969806, 2025). "Persistent CRP values greater than 100 mg/L on day four have also been associated with complications of pneumonia, while a failure to achieve a 50% reduction by day four is associated with an increased mortality." (PMID 41523477, 2025). "Multivariate logistic regression analysis identified pneumonia, external ventricular drainage, tracheotomy, procalcitonin, C-reactive protein, and albumin levels as independent risk factors for intracranial infections (p < 0.05)." (PMID 40529435, 2025). "In this study, we identified several key risk factors for predicting neonatal severe pneumonia, including respiratory rate, weight, CRP, NEU, HGB, UA, and BUN." (PMID 40529154, 2025). "Salivary C-reactive protein (CRP) has emerged as an alternative to serum CRP as a diagnostic marker of pneumonia and has been shown to rise during pneumonia and fall following infection resolution." (PMID 39907513, 2025). "Correlation analysis demonstrated that zinc concentration was significantly and negatively associated with the inflammatory marker CRP (r = -0.509, p < 0.001), RR (r = -0.363, p = 0.016), and pneumonia severity category (r = -0.395, p = 0.008)." (PMID 41487803, 2025). "Concentration of proGRP was associated with CRP (model coefficient was 0.20; P < 0.019) and both parameters contributed to classification of cases to pneumonia/COPD, ADC/SQCC, and NET categories (P < 0.004, in all cases)." (PMID 39703761, 2025). "In a multivariate analysis, elevated CRP concentrations were associated with an increased incidence of pneumonia." (PMID 40648912, 2025). "Lymphocytes play a crucial role in immune surveillance; their decrease suggests weakened immune defenses, while elevated CRP levels indicate increased inflammatory activity, further heightening the risk of infections such as pneumonia." (PMID 40034601, 2025). "In multivariate analysis, variables associated with the development of pneumonia were oxygen saturation (OR [95% CI] = 1.05 [1.00-1.11]) and CRP (OR [95% CI] = 1.71 [1.05–1.11])." (PMID 38475703, 2024). "Among older adults, those with frailty are more likely to experience pneumonia; frailty also associates with systemic inflammation including serum CRP in the cohort here studied." (PMID 38968193, 2024). "In contrast, low oxygen saturation and high levels of CRP at admission were associated with an increased risk of pneumonia development in patients admitted with influenza virus infection." (PMID 38475703, 2024). "White blood cells and C-reactive protein are important indicators of infection, and higher levels of white blood cells and C-reactive protein indicate a higher susceptibility to pneumonia." (PMID 39398953, 2024). "Calibration plots showed good calibration across the models, except at extreme levels of pneumonia risk, with the exploratory clinical and CRP model showing optimal calibration." (PMID 38968193, 2024). "A recent study found that elevated levels of serum CAR and CRP in middle-aged and older Finnish men were each associated with an increased risk of pneumonia." (PMID 38988811, 2024).
pneumonia (continued). "Concerning pneumonia, enhanced FEV1 (OR per SD = 0.93 [95% CI: 0.88, 0.98]) and FVC (OR per SD = 0.94 [95% CI: 0.88, 1.00]) lowered the infection risk, whereas elevated CRP, IL-6, and monocyte count magnified the risk of pneumonia." (PMID 39337223, 2024). "Chi-square test results revealed a significant association between the changes in CRP and the intensity of pneumonia, indicating that, with the intensification of pneumonia, the serum CRP increases as well." (PMID 39064460, 2024). "Several studies have demonstrated a strong association between an increase in CRP levels and the risk of severe pneumonia in children, as shown in one meta-analysis." (PMID 38167637, 2024). "The increase in the severity of CT thorax results (pneumonia with mediastinitis/pleural effusion) was associated with CRP values (p = 0.022)." (PMID 38474287, 2024). "In multivariate analysis, after adjustment for systolic blood pressure and CRP, lower eGFR (OR, 0.956; 95% CI, 0.920–0.993; p = 0.020) was significantly associated with pneumonia development." (PMID 38525743, 2024). "In our study, patients with severe disease had a median CRP of 12.3 mg/dl in comparison with 4.7 mg/dl in the non-severe category (p < 0.001), and a significant association was observed between levels of CRP and the development of pneumonia." (PMID 38475703, 2024). "Patients with undernutrition (WAZ <-2 SD), hypoxemia (SpO2 <95%), and having CRP >6 mg/dL were associated with clinical features of severe pneumonia (46.1% vs. 33.8%, 100% vs 47.3%, and 67.9% vs 48.5%, respectively, p < 0.05)." (PMID 38449934, 2024). "CRP level ≥ 50 mg/dL was associated with a sixfold increased risk pf severe pneumonia (aOR 6.11, 95% CI 3.86–9.68, P value < 0.0001)." (PMID 38167637, 2024). "In previous studies, patients with high CRP levels were at a significantly higher risk of developing severe pneumonia, requiring admission to the intensive care unit (ICU), and experiencing longer hospital stays." (PMID 38167637, 2024). "Regarding risk factors for severe pneumonia among children, our study found that the presence of smokers in the family, CRP level ≥ 50 mg/dL, respiratory syncytial virus, and H. influenzae were associated with a risk of severe disease." (PMID 38167637, 2024). "A retrospective cohort study demonstrated that a CRP level of 60 mg/L was a predictive cutoff value for pneumonia, showing that a CRP level of >60 mg/L was independently associated with a 3.59-fold increased risk of pneumonia." (PMID 37510151, 2023). "Replacing the classically used CRP with this combination assay improved the diagnostic accuracy to predict pneumonia or other SBIs." (PMID 37956117, 2023). "C-reactive protein, a routinely-available measure of inflammation, modestly improved pneumonia risk prediction over clinical factors." (PMID 38105941, 2023). "On the other hand, with the majority of patients in whom diagnostic doubt remained, CRP levels were useful to exclude pneumonia." (PMID 37296721, 2023). "In this study, CR-AB patients with pneumonia-associated bacteremia had a significantly higher level of CRP, a higher rate of CVVH treatment, and a longer ventilation time compared to those without bacteremia (all p ≤ 0.05)." (PMID 37768395, 2023). "It has been previously shown that a CRP > 100 mg/L is associated with pneumonia, or even bacterial pneumonia." (PMID 36830288, 2023). "CRP is a marker of inflammation, and elevated levels of CRP can be caused by other inflammatory conditions, for example, pneumonia." (PMID 37103558, 2023). "Calibration plots showed good calibration across the models, except at extreme levels of pneumonia risk, with the exploratory clinical and CRP model showing optimal calibration (Figure E1)." (PMID 38105941, 2023). "One study concluded that high CRP values are especially prevalent in pneumonia caused by S. pneumoniae or L. pneumophila." (PMID 37954793, 2023).
pneumonia (continued). "In our study, we found that gestational age, pneumonia, leukocytes, lymphocytes, red blood cells, platelets, CRP and blood sugar levels were correlated with the risk of surgical intervention in NEC." (PMID 37576139, 2023). "Another prospective cohort study indicated that serum Cu-Zn ratio was associated with the risk of incident pneumonia in Caucasian men, which was a better risk indicator than high-sensitivity C-reactive protein (hs-CRP)." (PMID 37917592, 2023). "In ICU patients with central venous catheters who have CR-AB pneumonia and are on mechanical ventilation, higher CRP levels and CVVH treatment are risk factors for developing bacteremia." (PMID 37768395, 2023). "Although 8 cases of Streptococcus pneumoniae and 7 cases of influenza A virus associated pneumonia were initially enrolled, after CRP detection and proteomic analysis, only 6 cases in each group were enough for ELISA determination." (PMID 37189569, 2023). "In univariate analyses, L3-SMI, L3-PMI, and all known risk factors (male sex, age, BMI, hypoalbuminemia, total lymphocyte count < 1.5 × 109/L, C-reactive protein ≥ 1.0 mg/dL and underlying pneumonia) emerged as predictive factors related to poor prognosis." (PMID 37240466, 2023). "Through multivariate correction analysis, we found that CRP, lymphocytes, and pneumonia were independent risk factors for the need for surgical intervention in NEC neonates." (PMID 37576139, 2023). "Multivariate logistic regression showed that the use of Thymalfasin was an independent protective factor of progressing to severe pneumonia, while CRP elevation was an independent risk factor." (PMID 37743481, 2023). "In conclusion, CRP and pneumonia are potential independent risk factors for surgical intervention in neonates with NEC, while lymphocytes are protective factors." (PMID 37576139, 2023). "The (binary) diagnostic accuracy for CRP-measurements at a cut-off 10 mg/L was also explored, as this is a common cut-off used, across tests and use cases, like tuberculosis and pneumonia." (PMID 36662693, 2023). "Age, CRP natural log-transformed value (InCRP), and monocyte percentage (%Mon) were found to be valid predictors of pneumonia risk." (PMID 37496884, 2023). "We found that low serum albumin level on hospital admission was associated to pneumonia, disease severity based on elevation of CRP level and was in fact a clear prognostic factor during one-, two- and five-year surveillance time." (PMID 35189828, 2022). "A unit increase in Cu/Zn-ratio was associated with an increased risk of pneumonia in analysis adjusted for potential confounders including C-reactive protein (HR 1.65; 95% CI 1.17–2.33)." (PMID 35781862, 2022). "We then considered a series of sensitivity analyses related to heterogeneity and pleiotropy, as well attempting to replicate the CRP → pneumonia susceptibility relationship with an independent CRP GWAS." (PMID 35768473, 2022). "One of the patients showed a highly increased CRP level of 21.1 mg/l with suspected pneumonia at his first visit, we excluded the associated blood culture from further analysis although it revealed a skin germ (Staphylococcus hominis)." (PMID 34297188, 2022). "Again, the patient showing CRP 21.1 mg/l was excluded from this analysis as his CRP was rather linked to the beginning pneumonia instead of mirroring chronic inflammation." (PMID 34297188, 2022). "In patient 4, after a first phase of clinical improvement accompanied by ApoA-I normalization and IL-8 decrease, ventilation-associated pneumonia and clinical deterioration were accompanied by C-reactive protein and IL-8 increase and ApoA-I decrease." (PMID 36225555, 2022). "More recent data from Malaysia involving 300 children with very severe pneumonia found that male sex, crepitations and elevated CRP were associated with higher risk of bacterial infection." (PMID 36370376, 2022).
pneumonia (continued). "One study found high levels of CRP was associated with high sensitivity (100%) and specificity (90%) for patients with symptomatic pneumonia and correlating radiographic features." (PMID 36211412, 2022). "Of particular concern was the significant elevation of plasma D-dimer and C-reactive protein (CRP) in each of the eight pneumonia cases, which correlated with an increased risk of a persisting cytokine storm." (PMID 36119044, 2022). "As a result, by combining S1P and CRP, we obtained a significantly higher diagnostic accuracy for the diagnosis of pneumonia in a patient with COPD in the emergency room setting." (PMID 35307030, 2022). "The present study also found that CRP > 15 mg/L was an independent risk factor for severe pneumonia in children with leukemia." (PMID 35601429, 2022). "ANA positivity wasn't associated with disease severity (p = 0.470), pneumonia severity (p = 0.291), outcome (p = 0.612), or markers of inflammation: CRP (p = 0.151), IL-6 (p = 0.652), ferritin (p = 0.112), SII (p = 0.722)." (PMID 36106319, 2022). "We uncovered evidence for non-zero genetic correlation and partial genetic causality between two biochemical indices (GGT and CRP) and pneumonia susceptibility." (PMID 35768473, 2022). "In the risk analysis of BMP formation in coinfection with AdV pneumonia, there were also differences in CRP and LDH levels." (PMID 35979256, 2022). "The positive sign of the genetic correlation estimates in these four instances, therefore, suggests that gallstones and gallbladder disease, elevated GGT, and elevated CRP would be risk factors for pneumonia." (PMID 35768473, 2022). "Current researches also included CRP as a biomarker for pneumonia in COPD patients, and they reported acceptable diagnostic accuracy (AUC from 0.63 to 0.84)." (PMID 35307030, 2022). "CRP has been shown to improve the diagnostic discriminatory power of models built on basic signs and symptoms during the prediction of patients with pneumonia." (PMID 35968461, 2022). "When the body has tissue damage caused by inflammation and infection, CRP will increase, which is an important indicator for the diagnosis of childhood pneumonia." (PMID 35795531, 2022). "Frequently observed CRP elevation in influenza-associated pneumonia seemed to be associated with disease severity." (PMID 33567507, 2021). "Similar findings of elevated white cell counts in hospitalised children with pneumonia were reported from Senegal, as well as high CRP levels (> 80 mg/dL) also being associated with radiologically confirmed pneumonia in Tanzanian children." (PMID 34412597, 2021). "There was an increased risk of SARS-CoV-2-associated pneumonia in younger patients with lower CRP levels, with bilateral infiltrate on chest x-ray and in the absence of abdominal pain." (PMID 33174170, 2021). "Pneumonia caused by SARS-CoV-2 is often accompanied by increased levels of C reactive protein (CRP), equivalent to those seen in bacterial pneumonia, and the secretion of hyaluronan, which affects oxygenation." (PMID 34564326, 2021). "Among the IA patients, we also observed higher proportions of cases with abnormally high levels of C-reactive protein and procalcitonin, which are both key inflammatory markers and are associated with poor prognosis such as pneumonia and even death." (PMID 33865314, 2021). "Multivariate analysis revealed lymphocytopenia < 1000/mm3 (odds ratio [OR]: 21.4; 95% CI: 2.8–162.9; p = 0.003) and high CRP level (OR: 45.7; 95% CI: 9.4–222.2; p < 0.001) to be independently associated with pneumonia." (PMID 33902480, 2021). "Several diagnostic biomarkers have been connected to pneumonia, among which are C-reactive protein (CRP), Procalcitonin (PCT), a Soluble triggering receptor expressed on myeloid cells-1 (STREM-1), CD163, and High Mobility Group Box-1(HMGB-1)." (PMID 34663864, 2021).